SAAL1 (serum amyloid A like 1)
Description:
Plays a role in promoting the proliferation of synovial fibroblasts in response to pro-inflammatory stimuli.
Synonyms: SPACIA1; FLJ41463
Tractability: PROTAC: ubiquitination databases record sites on it; its protein half-life has been measured.
Gene: Protein-coding gene on chromosome 11 (18,069,935 to 18,106,108, reverse strand). Ensembl gene ENSG00000166788.
Subcellular location: Nucleus
Subcellular location (Human Protein Atlas): Nucleoplasm
Gene Ontology:
Biological process: positive regulation of synoviocyte proliferation
Cellular component: nucleoplasm; nucleus
Genetic constraint (gnomAD): Loss-of-function variants: 28 observed, 32.74 expected, observed/expected ratio (o/e) 0.86, 90% interval 0.63 to 1.17. The upper end of that interval is the gene's LOEUF score, 1.17, which puts it in group 5 of 6, group 1 being the genes least tolerant of losing a copy. Missense variants: 367 observed, 382.26 expected, observed/expected ratio (o/e) 0.96, 90% interval 0.88 to 1.05. Synonymous variants: 145 observed, 139.33 expected, observed/expected ratio (o/e) 1.04, 90% interval 0.91 to 1.19.
Homologues: Orthologues: chimpanzee SAAL1 (99% identical), macaque SAAL1 (98% identical), dog SAAL1 (90% identical), pig SAAL1 (90% identical), guinea pig SAAL1 (89% identical), rabbit SAAL1 (87% identical), mouse Saal1 (80% identical), tropical clawed frog saal1 (54% identical), zebrafish saal1 (48% identical), Drosophila melanogaster CG30467 (19% identical). Paralogues in human: SAA4 (6% identical), SAA1 (5% identical), SAA2 (5% identical).
Diseases named in the same sentence as SAAL1 in open-access papers:
SAAL1 is named in the same sentence as 17 diseases in open-access papers, as found by Europe PMC text mining. Sharing a sentence is not in itself a finding about the gene and the disease. The quoted sentences say what the papers report.
hepatocellular carcinoma (3 papers, 2020 to 2023). A malignant tumor that arises from hepatocytes. "SAAL1 expression was significantly increased in hepatocellular carcinoma (HCC) and had something to do with shorter overall survival (OS) in HCC." (PMID 36973678, 2023). "Serum amyloid A-like 1 (SAAL1) was recently identified as a novel oncogene in hepatocellular carcinoma (HCC)." (PMID 35963646, 2022).
rheumatoid arthritis (2 papers, 2018 to 2020). A chronic, systemic autoimmune disorder characterized by inflammation in the synovial membranes and articular surfaces. "Upregulation of SAAL1 has been found in the foot joints of mice with collagen-induced arthritis and knockdown of SAAL1 can inhibit the proliferation of human rheumatoid arthritis synovial fibroblast (RASFs) in vitro." (PMID 32650537, 2020). "This study was performed to elucidate the molecular function of the synoviocyte proliferation-associated in collagen-induced arthritis (CIA) 1/serum amyloid A-like 1 (SPACIA1/SAAL1) in mice CIA, an animal model of rheumatoid arthritis (RA), and human RA-synovial fibroblasts (RASFs)." (PMID 30513680, 2018).
bladder cancer (1 paper, 2022). "SAAL1 overexpression was also associated with immunotherapy response and overall survival (OS) in bladder cancer (BLCA) patients who had received anti-PD-L1 treatment." (PMID 35963646, 2022).
breast carcinoma (1 paper, 2022). "Moreover, in the National Cancer Institute’s Clinical Proteomic Tumor Analysis Consortium (CPTAC) database, SAAL1 protein was significantly upregulated in breast cancer, colon cancer, ccRCC, UCEC, lung cancer, HNSC, GBM, and liver cancer compared with corresponding normal tissues." (PMID 35963646, 2022).
lung adenocarcinoma (1 paper, 2023). A carcinoma that arises from the lung and is characterized by the presence of malignant glandular epithelial cells. "At present, the correlation between SAAL1 and lung adenocarcinoma (LAC) remains unclear." (PMID 36973678, 2023).
lung carcinoma (1 paper, 2022). "In this regard, and because lung cancer is by far the most prevalent tumor, we limited our in vitro studies addressing the tumorigenic role of SAAL1 to the A549 cell line, in which SAAL1 is overexpressed." (PMID 35963646, 2022). "Lastly, we showed that SAAL1 silencing suppresses both malignant phenotype and expression of PD-L1 in lung cancer A549 cells in vitro." (PMID 35963646, 2022). "Since our analysis of CCLE datasets indicated that SAAL1 is overexpressed in lung cancer cell lines, we next explored the effect of SAAL1 on the proliferation, migration, and invasion of human lung A549 cancer cells." (PMID 35963646, 2022). "Lastly, the contribution of SAAL1 to tumorigenesis was suggested by our in vitro experiments, which showed that depletion of SAAL1 significantly inhibited proliferation, migration, and invasion, and reduced protein and mRNA expression of PD-L1 in lung cancer A549 cells." (PMID 35963646, 2022).
skin cancer (1 paper, 2022). "In turn, analysis of the Cancer Cell Line Encyclopedia (CCLE) datasets showed that SAAL1 was expressed in most cancer cell lines, and predominantly overexpressed in skin cancer cell lines." (PMID 35963646, 2022).
uterine cancer (1 paper, 2020). Primary or metastatic malignant neoplasm involving the uterine corpus and/or the cervix. "Although no information regarding SAAL1 and cancer was reported before, SAA was reported to be produced within tumor tissues including colorectal, ovarian, and uterine cancer." (PMID 32650537, 2020).
tumor (4 papers, 2018 to 2023). "To explore the potential role of SAAL1 in other cancers, we conducted a pan-cancer analysis of SAAL1 expression and its association with tumor microenvironment (TME) immunological profiles, sensitivity to chemotherapy agents, response to immunotherapy, and patient prognosis." (PMID 35963646, 2022). "Therefore, it may be hypothesized that mutations in the SAAL1 gene mainly account for its abnormal expression in a variety of tumor tissues." (PMID 35963646, 2022). "Thus, SAAL1 was not only upregulated in multiple tumor types but also associated with their prognosis, which suggested that SAAL1 may represent a diagnostic biomarker and a prognostic indicator for some tumors." (PMID 35963646, 2022). "Overall, our findings suggest that SAAL1 not only contributes to the tumor onset and development but is also closely related to their response to chemotherapy and immunotherapy." (PMID 35963646, 2022). "Overall, these analyses indicated that SAAL1 expression was correlated with that of immune checkpoint genes, albeit with different patterns in different tumor types." (PMID 35963646, 2022). "SAAL1 expression correlated with that of several immune-relevant genes, albeit with different patterns in different tumor types." (PMID 35963646, 2022). "First, the analysis of TCGA RNAseq and GENT databases showed that the expression of SAAL1 is significantly higher in HCC tumor tissues than that of the adjacent normal tissues." (PMID 32650537, 2020). "We are the first to show that the expression of SAAL1 was upregulated in HCC tumor tissues and correlated with poor overall survival in HCC patients." (PMID 32650537, 2020). "Our data showed that SAAL1 was significantly upregulated in HCC tumor tissues compared to the normal tissues." (PMID 32650537, 2020). "We found that SAAL1 was significantly upregulated in HCC tumor tissues when compared to the adjacent normal tissues and high expression of SAAL1 correlated with shorter overall survival in The Cancer Genome Atlas (TCGA) HCC database." (PMID 32650537, 2020). "Induction of SAA3 and SAAL1 protein expressions were also detected in tumor-bearing mouse lungs." (PMID 37620307, 2023). "Since apart from the mentioned study the role of SAAL1 in other cancer types has not been clarified, we undertook a comprehensive pan-cancer analysis of SAAL1 expression and its association with tumor-related features." (PMID 35963646, 2022). "Moreover, we detected tumor-specific correlations between SAAL1 expression and either chemoresistance or sensitivity to common chemotherapeutics." (PMID 35963646, 2022). "This suggested that promoter hypomethylation may be another reason for the high expression of SAAL1 in tumor tissues." (PMID 35963646, 2022). "Furthermore, when normal tissue data from GTEx database was combined with tumor tissue data from TCGA, SAAL1 mRNA was found to be significantly upregulated in 29/33 tumor types." (PMID 35963646, 2022). "In this regard, because high SAAL1 levels are present in blood, and overexpression occurs in many malignant tumors, blood-based SAAL1 testing may constitute an easily available strategy for tumor diagnosis." (PMID 35963646, 2022). "Although SAA family genes were reported to promote tumor angiogenesis and metastasis in several cancers, the role of SAAL1 is unknown in cancer and HCC tumorigenesis." (PMID 32650537, 2020). "Interestingly, our data indicate that SAAL1 may facilitate either resistance or sensitivity to chemotherapy and immunotherapies, depending on tumor type and expression levels." (PMID 35963646, 2022). "Since SAAL1 was highly expressed in most tumor types, the UCSC Xena database was used to examine the correlation between SAAL1 expression and clinical prognosis in different types of cancer." (PMID 35963646, 2022).
tumor (continued). "To do so, we applied a 3D Matrigel culture, which best recapitulates tumor growth in vivo, in SK-Hep1, PLC/PRF5, and Hep-3B lines and found that SAAL1 depletion greatly inhibited anchorage-independent growth in three HCC lines." (PMID 32650537, 2020). "We further observed that SAAL1 expression increased with tumor stage in ACC; this result suggested that SAAL1 may play an important role in the development of ACC." (PMID 35963646, 2022).
cancer (3 papers, 2020 to 2023). A tumor composed of atypical neoplastic, often pleomorphic cells that invade other tissues. "The results indicated that mutations were the main type of alterations in the SAAL1 gene in most cancer types evaluated." (PMID 35963646, 2022). "Based on data from the cBioPortal database, mutations were the most prevalent alterations in the SAAL1 gene among different cancers, with UCEC and SKCM showing in turn the highest mutation rates (>2%)." (PMID 35963646, 2022). "Hence, we examined the association between SAAL1 and immune checkpoint-related gene expression in different cancer types." (PMID 35963646, 2022). "SAAL1 was overexpressed in most malignant tumors in association with poor prognosis." (PMID 35963646, 2022). "Receiver operating characteristic (ROC) analysis showed that the area under the curve of SAAL1 in normal tissues and cancer tissues was 0.902, indicating the potential diagnostic value of SAAL1 in LAC." (PMID 36973678, 2023). "SAAL1 expression was also positively correlated with mismatch signatures in most types of cancer, except for CHOL, DLBC, and CESC." (PMID 35963646, 2022). "SAAL1 expression was positively correlated with immune signatures in most types of cancer, except for HYM, LAML, LUSC, OV, DLBC, GBM, PRAD, and SKCM." (PMID 35963646, 2022). "In summary, our study comprehensively analyzed the landscape of SAAL1 expression in different types of cancer." (PMID 35963646, 2022). "SAAL1 expression in cancer and paired normal adjacent tissue samples was then analyzed in The Cancer Genome Atlas (TCGA) datasets." (PMID 35963646, 2022). "Lastly, SAAL1 expression was negatively correlated with stromal signatures in most types of cancer, except for UVM, ACC, LIHC, and LGG." (PMID 35963646, 2022). "Nevertheless, we expect our findings to be useful for guiding future research on the role of SAAL1 in other types of tumors and to help design novel strategies to improve cancer treatment." (PMID 35963646, 2022). "In turn, assessment of proteomic data from the CPTAC database indicated that SAAL1 protein levels were significantly upregulated in eight types of cancer, compared with their normal counterparts." (PMID 35963646, 2022). "Analysis of CCLE datasets indicated that SAAL1 was expressed in most cancer cell lines, which suggested an important role in the development of multiple cancer types." (PMID 35963646, 2022). "We further assessed the expression of SAAL1 in different cancer stages and found stage-dependent increases in some tumors, including ACC, BLCA, and KIRC." (PMID 35963646, 2022). "We are the first to indicate that the depletion of SAAL1 affected the characteristics of cancer aggressiveness and inhibited the HGF/Met-driven Akt/mTOR signaling pathway." (PMID 32650537, 2020). "The area under the curve of SAAL1 was 0.902 in normal tissues and cancer tissues." (PMID 36973678, 2023). "Inhibiting SAAL1 expression in LAC cells promoted cancer cell apoptosis." (PMID 36973678, 2023). "SAAL1 is overexpressed in LUAD and is associated with poor survival of cancer patients." (PMID 36973678, 2023). "Inhibition of Serum Amyloid A-like 1 (SAAL1) expression could inhibit cancer progression and improve the prognosis of cancer patients." (PMID 36973678, 2023). "Inhibition of SAAL1 expression could inhibit cancer cell proliferation, which may be related to the decreased expression of cyclin D1 and Bcl-2 proteins." (PMID 36973678, 2023). "In addition, most of the 19 cancer types examined in the present study exhibited higher SAAL1 expression than their corresponding normal tissues in TCGA datasets." (PMID 35963646, 2022). "Moreover, pan-cancer KM analysis of OS indicated that patients with SAAL1 gene alterations had improved OS compared with those with unaltered SAAL1." (PMID 35963646, 2022). "Moreover, SAAL1 expression was also positively correlated with MSI in 13 cancer types, with TMB in 12 cancer types, and with neoantigen load in 4 cancer types." (PMID 35963646, 2022).
cancer (continued). "Inhibition of SAAL1 expression could regulate cancer growth via the cell cycle." (PMID 36973678, 2023). "Inhibition of SAAL1 expression could regulate cancer growth via cyclin D1 and Bcl-2." (PMID 36973678, 2023). "Therefore, bioinformatics was applied to investigate the SAAL1 levels in cancer tissues." (PMID 36973678, 2023). "Specifically, it is worth noting that SAAL1 was positively correlated with PD-L1, CTLA-4, and LAG-3 in most cancer types." (PMID 35963646, 2022). "Therefore, SAAL1 might be a pan-cancer biomarker of favorable prognosis for ICB therapy." (PMID 35963646, 2022). "Functionally, we showed that the depletion of SAAL1 significantly reduced cell proliferation, 3D colony formation, and migration/invasion abilities of HCC cancer cells." (PMID 32650537, 2020). "The results showed that SAAL1 was significantly depleted at the mRNA and protein level, respectively, in three HCC cancer cell lines, Hep3B, SK-Hep1, and PLC/PRF5 using qRT-PCR and Western blot analysis." (PMID 32650537, 2020). "SAAL1 level was elevated in LAC tissues, and was observed in cancer tissues of dead patients." (PMID 36973678, 2023). "To further investigate the potential correlation between SAAL1 expression and anticancer drug sensitivity, we accessed the CellMiner database to retrieve drug sensitivity and RNA-Seq information for the NCI-60 panel of cancer cell lines." (PMID 35963646, 2022). "Moreover, we found that cancer patients with SAAL1 gene alterations had better OS than those without alterations in this gene." (PMID 35963646, 2022).
infection (2 papers, 2020 to 2021). The state of being infected such as from the introduction of a foreign agent such as serum, vaccine, antigenic substance or organism. "It was explained in an early study that activation of serum amyloid A like 1 (SAAL1) mainly affected the acute phase response, a response due to environmental insults such as tissue damage, infection, and surgery." (PMID 34828008, 2021).
SAAL1 also shares sentences with these, for which no sentence is quoted: amyloidosis (1 paper); Arthritis (1); colon cancer (1); liver cancer (1); pancreatic cancer (1); synovitis (1).